ENSG00000258881 (novel protein)
Gene: Protein-coding gene on chromosome 2 (70,939,318 to 70,995,336, reverse strand). Ensembl gene ENSG00000258881.
Genetic constraint (gnomAD): Loss-of-function variants: 9 observed, 15.45 expected, observed/expected ratio (o/e) 0.58, 90% interval 0.35 to 1.02. Missense variants: 150 observed, 171.47 expected, observed/expected ratio (o/e) 0.87, 90% interval 0.76 to 1. Synonymous variants: 66 observed, 71.91 expected, observed/expected ratio (o/e) 0.92, 90% interval 0.75 to 1.13.